MIR6795 (microRNA 6795)
Synonyms: hsa-mir-6795
Gene: MicroRNA gene on chromosome 19 (15,179,283 to 15,179,350, reverse strand). Ensembl gene ENSG00000275711.
Homologues: Orthologues: chimpanzee MIR6795 (100% identical).